IDO1 (indoleamine 2,3-dioxygenase 1)
Diseases named in the same sentence as IDO1 in open-access papers (continued):
Sharing a sentence is not in itself a finding about the gene and the disease.
breast carcinoma (continued). "Through analysis of the TCGA-TNBC database, we found that the expression levels of IDO1 in breast cancer tissue were significantly greater than those in normal breast tissue." (PMID 40217479, 2025). "In the WT 4T1 breast cancer model with high IDO1 expression, the efficacy of STING-NP monotherapy was attenuated and lower than combinatory iBINP therapy." (PMID 41129257, 2025). "A preclinical study revealed that combining the IDO1 inhibitor D1MT with the CXCR4 antagonist AMD3465 significantly delayed breast cancer bone metastasis progression in animal models." (PMID 40496774, 2025). "IDO1 regulates the cell cycle distribution and exhibits anti-apoptotic effects in breast cancer cells." (PMID 39973065, 2025). "Results of this study will provide novel information on the pathophysiological expression of IDO1 in rabbits and the molecular profile of pet rabbit mammary carcinomas." (PMID 39061522, 2024). "In pet rabbit mammary carcinomas, the detected IDO1 expression is regarded as a mainly constitutive event due to the presence of only sparse immune cell infiltrates in most tumors." (PMID 39061522, 2024). "Comparable to the findings in examined rabbit tumors, human breast cancer samples displayed a marked variance in the percentage of immunopositive tumor cells, and most IDO1-positive tumors (59%) harbored 1–10% positive tumor cells." (PMID 39061522, 2024). "Regarding tumor type, high IDO1 expression was commonly seen in uterine cancer (54.2% of uterine tumors), followed by ovarian (37.2%), lung (25.0%), esophageal (17.6%), and breast cancer (16.3%)." (PMID 38632994, 2024). "IDO1 is formed primarily by stimulated macrophages, and overexpression is correlated with poor prognosis in breast cancer patients." (PMID 39199788, 2024). "The PCR results showed that in contrast to normal cells, IDO1 was found to be significantly highly expressed in breast cancer cells and hepatocellular carcinoma cells, and significantly lowly expressed in gastric cancer cells." (PMID 38539263, 2024). "IDO1 inhibitors have reached clinical trials for targeting various solid tumors including breast cancers." (PMID 39199788, 2024). "Since previous studies revealed similarities between human breast cancer and pet rabbit mammary carcinomas, this study investigated IDO1 immunostaining in 96 mammary carcinomas of 96 pet rabbits with an average age of 5.5 years." (PMID 39061522, 2024). "We found that breast cancer tissues significantly expressed IDO-1 compared to healthy breast tissues, especially in TNBC subtype." (PMID 37981615, 2024). "In TNBC, IFNγ stimulation is particularly important, as it enhances the expression of the immune checkpoint and tryptophan catabolic enzyme indoleamine 2,3-dioxygenase 1 (IDO1) by breast cancer cells." (PMID 39282472, 2024). "In rabbit mammary carcinomas, this study showed a statistically significant correlation between a rise in IDO1 and an increase in ER-α expression." (PMID 39061522, 2024). "Elevated IDO1 expression and PS were positively correlated with a better prognosis in breast cancer." (PMID 38780888, 2024). "In this study, a pathomic model based on ML was constructed to predict IDO1 status and its relationship with prognosis directly from the six pathomic features of H&E-stained breast cancer sections." (PMID 38780888, 2024). "This study confirmed that the expression of the IDO1 protein is also present in pet rabbit mammary carcinomas." (PMID 39061522, 2024). "The aim of this retrospective immunohistochemical study was to examine the expression of IDO1 in pet rabbit mammary carcinomas and adjacent normal tissue to gain knowledge on the pathophysiological expression patterns of this enzyme in rabbits." (PMID 39061522, 2024). "IDO1 was found to be significantly highly expressed in breast cancer cells MCF-7 and MDA-MB-231 and hepatocellular carcinoma cells HepG2, HUH-7, and SMMC-7721 in comparison to normal cells." (PMID 38539263, 2024).
breast carcinoma (continued). "In human breast cancer, the immunosuppressive enzyme indoleamine 2,3-dioxygenase 1 (IDO1) represents a prognostic biomarker and possible therapeutic target." (PMID 39061522, 2024). "This retrospective immunohistochemical study examined IDO1 in 96 pet rabbit mammary carcinomas with known mitotic count, hormone receptor status, and percentage of stromal tumor infiltrating lymphocytes (TILs)." (PMID 39061522, 2024). "In a study of breast cancer cells, tumor infiltration by anti-tumor NKT cells and the expression of PD-L1, IDO1 and FoxP3 were associated with high levels of glycolysis, an observation partly attributed to the intermediate expression of IL-17." (PMID 37296860, 2023). "Consistent results were obtained in the human HCC cell line SMMC-7721 and the mouse breast cancer cell line 4T1 that IDO1 overexpression inhibited HSV-1 replication, suggesting the universality of our findings." (PMID 37296221, 2023). "The results indicate that overexpression of IDO1 significantly promotes the development of breast cancer." (PMID 36550159, 2022). "Independent studies have stated that miR-200c-3p overexpression resulted in a downregulation of PD-L1 and IDO1 in adipose-derived mesenchymal stem cells, and decreased PD-L1 levels in ovarian cancer and breast cancer cells." (PMID 36469564, 2022). "In the past decade, numerous studies have observed high IDO1 levels in human tumors, including glioblastoma, head and neck squamous cell carcinoma, breast cancer adrenocortical carcinoma, esophageal squamous cell carcinoma, gastric cancer, and colon cancer." (PMID 35681736, 2022). "Lastly, Dox and PTX have also been evaluated in combination with IDO-1 inhibitor to treat breast cancer." (PMID 35335881, 2022). "In a study of chemokine CXC motif ligand 12 (CXCL12), a prognosis factor similar to IDO1, a high CXCL12 expression was associated with a shorter OS in esophagogastric, pancreatic, or lung cancer, while the opposite was the case for breast cancer." (PMID 36212460, 2022). "High microvascular density and worse prognosis of breast cancer is closely related to the expression of IDO1." (PMID 35681736, 2022). "In conclusion, the results indicate that overexpression of IDO1 significantly promotes the development of breast cancer." (PMID 36550159, 2022). "We further examined the expression of IDO1 and PD-L1 in breast cancer patients by analyzing single-cell RNA-sequencing data from The Single Cell Expression Atlas." (PMID 34381711, 2021). "The results showed that the level of PD-L1 and IDO1 were higher in TNBC than that in Luminal A positive breast cancer." (PMID 34381711, 2021). "Accordingly, we examined the level of IDO1 in breast cancer samples by using RNA-sequencing data from GEPIA." (PMID 34381711, 2021). "Tumour cells expressing IDO1 were found in prostatic, endometrial, bladder, colorectal, pancreatic gastric, cervical, breast carcinomas, and also in many other types of cancer." (PMID 33541164, 2021). "Their observations imply that IDO1 expression contributes to the resistance of breast cancer to anti-PD-1/PD-L1 treatment." (PMID 33747948, 2021). "Macrophages can also respond to immunotherapy by inhibiting NK cell‐mediated ADCC and T cell‐mediated cytotoxicity in breast cancers and lymphomas through the upregulation of PD‐L1 and IDO1." (PMID 33252831, 2021). "The RNA-sequencing data from the Gene Expression Profiling Interactive Analysis (GEPIA) revealed that expression of PD-L1 was positively correlated with that of IDO1 in breast cancer patients." (PMID 34381711, 2021). "Taken together, the outcomes of these studies suggest that IDO1 inhibitors can be used as standard-of-care treatment for breast cancer and other solid tumors, alone or in combination with other cancer therapeutic strategies." (PMID 33747948, 2021).
breast carcinoma (continued). "Having confirmed the high concentration of TNFα in bevacizumab-resistant breast cancer and inhibition of TNFα suppressed tumor migration and IDO1 expression in vitro, we treated MDA-MB-231-bearing mice with bevacizumab, anti-TNFα nanobody, both, or PBS." (PMID 33214550, 2020). "To further investigate the role of IDO1 in gynaecologic and breast cancers, we evaluated its co‐expression related genes." (PMID 32227579, 2020). "Our study is the most comprehensive study characterizing the expression pattern of IDO1 together with its related genetic features and prognostic values in gynaecologic and breast cancers." (PMID 32227579, 2020). "Second, tumor-infiltrating T cells jointly induce the expression of IDO1 and TrpRS in breast cancer, colon carcinoma, and B-cell lymphoma by secreting IFN-γ." (PMID 33271945, 2020). "We stimulated 4T1 breast cancer cells with conditional medium of M2b macrophages and control medium, and the results showed that IDO1 was remarkably increased in TNFα enriched conditional medium." (PMID 33214550, 2020). "When taking breast cancer subtypes into account, we found that IDO1 was highly expressed in ER‐negative, PR‐negative and Her2‐negative samples and basal‐like breast cancer than other types breast cancers." (PMID 32227579, 2020). "Existing preclinical researches have clearly confirmed that paclitaxel combined IDO1 inhibitors would restore the proliferation ability and cytotoxic response of TILs and achieved synergistic antitumor effect in breast cancer and ovarian cancer." (PMID 32733806, 2020). "These were glioma A172 only with TDO2 expression, ovarian SKOV3, which only expresses IDO1 and finally the breast cancer cell line BT549, which expresses both enzyme." (PMID 31795096, 2019). "Additional immunotherapeutic agents, including agents targeting immune-metabolic pathways (adenosine and indoleamine 2,3-dioxygenase 1 [IDO1]) or T-cell agonists (OX40) are being evaluated in conjunction with anti-PD-1/L1 in breast cancer." (PMID 31602395, 2019). "IDO1-expressing breast cancer cell line MCF-7 and gastric carcinoma cell line SGC-7901 were chosen as cell models to elucidate the potential role of H2S in the regulation of IDO1." (PMID 30777103, 2019). "Given the correlation between H2S and IDO1 found in Cse−/− mice, breast cancer cell line MCF-7 and gastric carcinoma cell line SGC-7901, it is necessary to find the universality of this correlation in human cancer samples." (PMID 30777103, 2019). "For completeness we also assessed the association of IDO1 and KAT3 with all-cancer and common cancers including prostate, lung and bronchus, and breast cancer." (PMID 31186442, 2019). "A previous study found that miR-153 targeted IDO1 in graft-versus-host disease and colon cancer, and miR-448 targeted IDO1 in breast cancer." (PMID 31391111, 2019). "MDSCs can suppress antitumor immune responses through STAT3-dependent IDO1 expression in breast cancer." (PMID 30068361, 2018). "High IDO1 expression positively correlates with microvessel density and poor prognosis in breast cancer patients." (PMID 30068361, 2018). "In 4T1 breast cancer pulmonary metastases and oxygen-induced retinopathy mouse models, IDO1 ablation was sufficient to reduce pathological neovascularization in both lung metastases and reinopathy." (PMID 30068361, 2018). "First, breast cancer cells, in part via IFNγ, induce IDO1 expression in endothelial cells, leading to tryptophan degradation." (PMID 29156701, 2017). "Here we showed that both breast cancer andnormal ASCs can produce regulatory moleculessuch as IDO1, IDO2, and HLA-G5." (PMID 28367424, 2017). "In breast cancer, high IDO1 expression correlated with lymph node involvement and with worse recurrence-free survival." (PMID 29156701, 2017). "In a tumour tissue array, the intensity and area of vascular IDO1 staining positively correlated with the stage of breast cancer." (PMID 29156701, 2017).
breast carcinoma (continued). "Indoleamine 2,3-dioxygenase 1 (IDO1) overexpresses in variety types of tumours including breast cancer." (PMID 29156701, 2017). "The pathologic significance of IDO1 in breast cancer involves in a complex of regulatory interactions of metabolism and immune." (PMID 29156701, 2017). "Recent studies suggested that IFNγ can induce an overexpression of IDO1 in varieties types of tumours including breast cancer, followed by a breakdown of tryptophan." (PMID 29156701, 2017). "The use of small interfering RNA to knock down IDO1 expression in a mouse model of breast cancer resulted in the enhancement of the immunogenicity of a DC-based vaccine." (PMID 25815345, 2015). "More important, high COX-2 in tumors and high IDO1 expression in CAFs predicted worse disease-free and metastasis-free survivals in breast cancer patients (P < 0.0001)." (PMID 25060643, 2014). "The role of the tryptophan-catabolizing enzyme, indoleamine 2,3-dioxygenase (IDO1), in tumor escape and metastasis formation was analyzed using two pairs of Ido1+ and Ido1− murine breast cancer cell lines." (PMID 22654951, 2012). "Also, 4T1/IDO1+ breast cancer cells showed an increased proliferation in BALB/c mice compared to 4T1/IDO1− breast cancer cells." (PMID 40214422, 2025). "Importantly, IDO1 expression was positively correlated with Pyk2 phosphorylation (R = 0.3, p = 0.00042) in 136 patients with breast cancer." (PMID 39585774, 2025). "To clarify the clinical significance of IDO1 and Pyk2 phosphorylation in the progression of breast cancer, we examined the protein expression of IDO1 and Pyk2 phosphorylation in the tumor tissues of 136 patients with breast cancer." (PMID 39585774, 2025). "Additionally, the downregulation of IDO1 led to the suppression of breast cancer cell migration, as evidenced by the Transwell migration assay and the scratch wound healing assay." (PMID 40217479, 2025). "Additionally, podoplanin-positive CAFs contribute to trastuzumab resistance in HER2-positive breast cancer by secreting immunosuppressive factors, including indoleamine 2,3-dioxygenase 1 (IDO1) as well as tryptophan 2,3-dioxygenase 2 (TDO2)." (PMID 41029829, 2025). "Herein, tumor NOS2 and IDO1 are inversely correlated with ER– breast cancer survival." (PMID 40663402, 2025). "Furthermore, in BALB/c mice inoculated with 4T1/IDO1+ breast cancer cells, an increase in tumor growth and lung metastases was reported." (PMID 40214422, 2025). "The high expression levels of IDO1 in mouse breast cancer tumor tissues in vivo cannot be ignored." (PMID 39661740, 2025). "IDO1 expression has also been extensively studied in the context of breast cancer." (PMID 41332472, 2025). "Interestingly, the inhibitory effect of KYNU on breast cancer is importantly related to the expression of IDO1/TDO2." (PMID 41282989, 2025). "Additionally, BRCA1/2-deficient breast cancers have a higher expression of immunosuppressive molecules compared with BRCA1-WT breast cancers in WSI and TCGA cohorts, including CTLA-4, IDO1, and LAG3." (PMID 40830526, 2025). "In ER+ breast cancer, increased IDO1 expression may deplete tryptophan, suppress T cells, and aid immune evasion." (PMID 40772270, 2025). "Thus, given the significant potential of IDO1 and Pyk2 as therapeutic targets for breast cancer, further clinical studies are necessary to validate their potential applications in predicting the potential response of CCB to combination immunotherapy." (PMID 39585774, 2025). "Thus, IDO1 can promote the proliferation and migration of breast cancer cells, thereby playing a pivotal role in the development of TNBC, which further substantiates its critical function in TNBC." (PMID 40217479, 2025). "Due to the selective expression of IDO1 in tumor cells, IDO1 inhibition in rabbit mammary carcinomas may have the benefit of directly targeting tumor cells without causing possible interfering effects also in other cell populations." (PMID 39061522, 2024).
breast carcinoma (continued). "This study demonstrated that a pathomic model based on ML and histopathological image features could predict IDO1 status and prognosis in breast cancer patients." (PMID 38780888, 2024). "This suggests that healthcare professionals may use PS as a biomarker to improve prognosis predictions of breast cancer patients and select patients who would benefit more from IDO1 inhibitor immunotherapy." (PMID 38780888, 2024). "IDO1 inhibition could reverse the immunosuppressive effects of IDO1 and improve breast cancer outcomes." (PMID 38780888, 2024). "Thus, further studies are necessary to reveal if IDO1 inhibition in pet rabbit mammary carcinomas will stimulate immune cell infiltration within the tumor area." (PMID 39061522, 2024). "Human breast cancer may express the immunosuppressive enzyme indoleamine 2,3-dioxygenase 1 (IDO1), that represents a prognostic biomarker and a possible therapeutic target." (PMID 39061522, 2024). "The observation that most rabbit mammary carcinomas were IDO1-positive and showed a cold tumor status may suggest that IDO1 could be involved in impacting anti-cancer immune defenses also in pet rabbit mammary carcinomas." (PMID 39061522, 2024). "Since examined sections only represent a snapshot of the findings during tissue selection, IDO1 expression during early tumorigenesis could have contributed to the low number of TILs in most of the examined rabbit mammary carcinomas." (PMID 39061522, 2024). "It was observed that IDO1 expression and PS levels were elevated in breast cancer patients." (PMID 38780888, 2024). "The lower IDO1 expression in rabbit mammary carcinomas with reduced ER-α levels may suggest that, in these tumors, alternative tumor-promoting mechanisms are upregulated." (PMID 39061522, 2024). "In human breast cancer, IDO1 expression has been reported in all molecular subtypes." (PMID 39061522, 2024). "IDO1-positive pet rabbit mammary carcinomas showed two different staining patterns of tumor cells." (PMID 39061522, 2024). "As a result, insights into the IDO1 inhibition mechanism and comprehensible clinical trial design are required for IDO1-targeted small molecule drug development for solid tumors including breast cancer." (PMID 39199788, 2024). "In human breast cancer, all molecular subtypes can be IDO1-positive, although, the percentages of positive tumors may vary between breast cancer types." (PMID 39061522, 2024). "The absence of a statistically significant association between these two parameters and IDO1 immunostaining may suggest that IDO1 represents an independent prognostic marker also in pet rabbit mammary carcinomas." (PMID 39061522, 2024). "Besides, the overall survival time of breast cancer patients with at least one gene mutation in PRKDC, NOS2, ARG1, and IDO1 (1191 patients) was significantly shorter compared with patients without the mutations (4575 patients)." (PMID 36373232, 2023). "Similarly, as in the publications for breast cancer, IDO-1 was also discussed in only one of the pancreatic cancer trials reviewed here-in." (PMID 37181043, 2023). "Indoleamine 2,3-dioxygenase 1 (IDO1) inhibition is another metabolic approach promoting Vγ9Vδ2 T-cell cytotoxicity against human breast cancer cells and pancreatic ductal adenocarcinoma (PDAC) cells by enhancing perforin production, degranulation, and cytokine production." (PMID 37143664, 2023). "As such, IDO-1 could be considered as an important emerging biomarker related to breast cancer treatment, and especially in relation to immune-based therapy." (PMID 37181043, 2023). "For example, up-regulation of the Trp catabolizing enzyme indoleamine 2,3-dioxygenase 1 (IDO-1) in circulating immune cells was reported for several cancer entities, including colorectal, lung and breast cancer, leading to increased serum concentrations of Kyn." (PMID 35160173, 2022).